IL6 (interleukin 6)
Diseases named in the same sentence as IL6 in open-access papers (continued):
Sharing a sentence is not in itself a finding about the gene and the disease.
lung carcinoma (continued). "By observing the changes of inflammatory cytokine levels after chemotherapy intervention, we found that the difference between IL-6 and TNF-α of the 85 patients with lung cancer was gradually reduced after chemotherapy." (PMID 40265008, 2025). "In lung cancer, IL‐6 activates STAT3 to induce IDO1, which in turn produces Kyn and KYNA to activate AhR and induce IL‐6 expression." (PMID 40103267, 2025). "CAFs promote EMT in lung cancer cells by delivering Snail-1 proteins and microRNAs miR-210 and miR-224 through exosomes, as well as by secreting IL-6 and TGF-β IL-6 plays a role in the interactions between CAFs and cancer cells in lung cancer." (PMID 40136652, 2025). "During the lung cancer brain metastasis, lung cancer cells secrete IL-8, MIF, and PAI-1, which activate astrocytes and induce the expression of TNF-α, IL-1β, and IL-6, thereby promoting the proliferation of cancer cells." (PMID 41268299, 2025). "Conversely, M2-like microglia secrete IL-6, IL-8, IGF and CCL20, which aid in maintaining lung cancer stemness and immunosuppressive cell recruitment." (PMID 41429896, 2025). "Conversely, SIK3 demonstrates a dual role: it promotes cell proliferation in breast and ovarian cancers by facilitating the G1/S transition, but inhibits proliferation in non‐small cell lung cancer (NSCLC) through modulation of AP1 and IL6 signaling." (PMID 39877288, 2025). "Previous studies have shown that, CAFs in the TME can secrete IL-6, which stimulates STAT3 signaling in lung cancer cells and promotes metastasis." (PMID 38424624, 2024). "Lung cancer cells applied with PI3K, Akt, and NF-κB pharmacological inhibitors all suppress the cigarette smoke-induced promotion of IL-6 generation and cell migration." (PMID 38993553, 2024). "Stromal fibroblasts release IL-6, CSF3, and Activin-A, which promote the dedifferentiation of lung carcinoma cells to cancer stem cells." (PMID 39338937, 2024). "Thus, targeting IL-6 may be a potential pharmacological approach for treating lung cancer." (PMID 38424624, 2024). "Analysis of the predictive efficacy of postoperative 1dCRP, IL-6, IGF-1, and IGF-3 combined methods in predicting secondary lung infection in elderly patients after lung cancer surgery." (PMID 39495987, 2024). "IL6/STAT3 pathway is activated in KRAS-driven tumors and can contribute to tumor occurrence and drug resistance in lung cancer." (PMID 39191757, 2024). "Statins inhibit chemokine (C-C motif) ligand 3 (CCL3) secretion by primary lung cancer cells and suppress IL-6 and CCL2 production by mesenchymal stromal cells (MSCs), and disrupt the communication between lung cancer cells and MSCs." (PMID 38362156, 2024). "The combined use of specific cytokines showed promise in lung cancer diagnosis, with IL-8, IL-10, and MCP-1 achieving 76% sensitivity and 79% specificity in AAs and IL-6 and IL-8 combined offering 76% sensitivity and 74% specificity in WAs." (PMID 38276239, 2024). "Leptin dose-dependently promotes naïve CD4+ T cell proliferation and polarizes CD4+ T cells towards a Th1 phenotype, which in turn facilitates lung cancer secretion of inflammatory cytokines such as TNF-α and IL-6, promoting lung cancer bone metastasis." (PMID 38571500, 2024). "The ability of serum IL-6 combined with IL-8 and CEA to differentiate lung cancer from health controls highlights the diagnostic potential of serum IL-6 for lung cancer." (PMID 38529301, 2024). "The combined use of specific cytokines showed promise in diagnosing lung cancer, with IL-8, IL-10, and MCP-1 achieving 76% sensitivity and 79% specificity in AAs, and IL-6 and IL-8 combined offering 76% sensitivity and 74% specificity in WAs." (PMID 38276239, 2024). "In brief, preclinical evidence reveals that targeting IL-6, STAT3, MAPK3, or AKT1 provides an effective way to suppress lung cancer." (PMID 39258670, 2024).
lung carcinoma (continued). "Several cytokines, such as interleukin-6 (IL-6), oncostatin M, and tumor necrosis factor-α (TNFα), induce CYP19A1 gene expression in lung cancer through the regulation of estrogen synthesis." (PMID 37047797, 2023). "Interleukin-6 (IL-6) and Interleukin-8 (IL-8) are some of the common SASP factors inducing tumorigenesis in breast, prostate, and lung cancers." (PMID 36769195, 2023). "Together, these results revealed that Q11 can inhibit the activation of the IL‐6/STAT3 pathway and the MAPK/ERK pathway in lung cancer." (PMID 37875398, 2023). "Compared to the sham group, the expression of IL‐6, phosphorylated STAT3 and two major MAPKs subtypes (phosphorylated p38‐MAPK and phosphorylated ERK1/2) were significantly increased in the lung cancer model group." (PMID 37875398, 2023). "The study measured the concentration of IFN-γ, TNF-α, IL-1β, IL-2, IL-4, IL-6, IL-10, and IL-12p70, in venous blood and BALF of a total of 33 patients with lung cancer and 33 patients with benign lung diseases." (PMID 37373987, 2023). "The engagement of TLR3/4 was reported to induce increases in the production of IL-6, CCL2, CCL20, VEGF, and MMP2 through NF-κB activation, thereby enhancing lung cancer migration and invasion." (PMID 37287005, 2023). "In contrast to the results obtained in our research, other studies obtained significantly higher values of IL-6 and IL-1β in BALF in patients with lung cancer compared to the control group." (PMID 37373987, 2023). "In lung cancer, Chen and his coworkers discovered that the impression of many axes “mir-125b-5p-ACE-2-IL-6” in (mir-125b-5p) suppressed the impression of IL-6 by encouraging the upregulation of ACE-2." (PMID 37124230, 2023). "The engagement of TLRs induced NF-κB activation via the TRAF6-TAK1 signaling axis and increases in the production of IL-6, CCL2, CCL20, vascular endothelial growth factor (VEGF), and MMP2, thereby enhancing lung cancer migration and invasion." (PMID 37287005, 2023). "Previous studies have also found that capsaicin supplementation in lung cancer bearing mice considerably prevented the increaseof TNF-α, IL-6, COX-2 and NF-κB." (PMID 36771198, 2023). "Compared to the SPHK2 inhibitor Opaganib, which only reduces the release of IL-6 from PBMC of lung cancer origin, inhibition of SPHK1 by PF543 can down-regulate both TNF-α and IL-6 release and more effectively inhibit lung cancer progression." (PMID 36823149, 2023). "For example, IL-6 and VEGF have been reported to be increased by estrogenic effects in NSCLC mouse models and are known to be produced by CAFs in lung cancer." (PMID 37509283, 2023). "For example, IL-6, IL-8, and IL-17 have been shown to increase VEGF expression in lung cancer cells, which increases angiogenesis." (PMID 37760616, 2023). "A novel signaling cascade, IL-6/STAT3/HIF-1α, has been discovered in numerous cancer types including pancreatic cancer, prostate cancer, lung cancer, colon cancer, and malignant glioma." (PMID 36814597, 2023). "The interactions between stromal cells and tumor cells activate various molecular signaling pathways, such as interleukin-6/STAT-3/c-Myc pathway, and TGF-β pathway in prostate cancer, lung cancer, and colorectal cancer." (PMID 37173640, 2023). "The results demonstrated that TGF-β1 levels were higher in patients with lung cancer compared to those with benign diseases, with a significant correlation found between TGF-β1 and IL-6 in BALF." (PMID 37373987, 2023). "Because previous evidence showed that cytokine IL6 and IL8 secretion promoted necrosis in glioblastoma, we examined these two cytokines in lung cancer cells treated with 8PN or/and EGFR TKIs." (PMID 37013960, 2023).
lung carcinoma (continued). "In lung cancer, high expression of S1P increases the release of TNF-α and IL-6 from PBMC of lung cancer origin." (PMID 36823149, 2023). "In an in vitro model, astrocytes were shown to secrete inflammatory cytokines (IL-6, tumor necrosis factor-α (TNF-α) and IL-1β) in the presence of lung cancer cells, resulting in increased proliferation of the tumor cells." (PMID 37749707, 2023). "The median IL-6, TNFα, IL-1β, and IFN-γ values were higher in lung cancer cases than in the subcohort." (PMID 38067398, 2023). "Data reported in the literature have shown that WNT5A can regulate the secretion of IL-6 and CCL2 in other types of cancer, including melanoma and non–small cell lung cancer." (PMID 37607007, 2023). "The interleukin-6 (IL-6)/Janus kinase (JAK)/signal transducer and activator of transcription 3 (STAT3) signaling pathway is overactive in multiple cancer types, including lung cancer, and is important in cancer pathogenesis." (PMID 34773474, 2022). "Of the 12 cytokines, six (IL-6, IL-8, IL-10, IL-12p70, IFN-γ, and TNF-α) displayed a higher level in plasma of lung cancer patients compared with cancer-free smokers (All p < 0.001)." (PMID 36498497, 2022). "Further verification found that six hub genes were screened in relation to lung cancer, including mTOR, NF1, CHD7, ETS1, IL-6, and COL1A1." (PMID 36211008, 2022). "We also examined the effect of independent variables (subtype and stage of lung cancer etc.)on hepcidin, IL-6, and TNF-α concentrations in male lung cancer patients." (PMID 36612220, 2022). "IL-6 regulates the JAK2/STAT3 axis to up-regulate DNA methyltransferase 1(DNMT1), enhancing stem cell proliferation in lung cancer." (PMID 36550571, 2022). "Overexpression of Snail1 in lung cancer cells shows increased production of inflammatory cytokines TNF-α, IL-1β, and IL-6 by regulating macrophage activation." (PMID 36159784, 2022). "According to a recent study by our group, IL-6 was not significantly increased in BALF of patients with untreated lung cancer and other lung diseases (sarcoidosis, ILD), deeming IL-6 appropriate as biomarker of unspecific inflammation." (PMID 34347128, 2022). "Here, we evaluated the expression of NF-κB, AICDA, Akt, IL-6, Jak2, and Stat3 by EGFR-TKI-resistant lung adenocarcinoma (LAC), and found that NF-κB and AICDA are major players in the acquired resistance of lung cancer to TKIs." (PMID 35740609, 2022). "The mRNA expression of CCL3, CCL4, and CSF1 was significantly upregulated in IL17D–expressing A549 cells compared with that in control cells, whereas IL17D overexpression in the murine lung cancer cell line LLC1 increased Ccl3, Ccl4, and Il6 expression." (PMID 35939336, 2022). "Previous reports have demonstrated that TLR3/4 activation can increase the production of IL-6, CCL2, MMP2, and CCL20 cytokines by promoting TRAF6 ubiquitination and autophagy induction, thereby facilitating the migration and invasion of lung cancer cells." (PMID 35422093, 2022). "Among the studied chemokines and cytokines, IL-6, which was reported to induce EGFR-TKI resistance in EGFR-mutant lung cancer through paracrine STAT3 activation, was highly expressed in EGFR wild-type A549 cells in our study." (PMID 36612121, 2022). "Treatment with I3C can also suppress the progression of inflammation-related lung cancer in mice by reducing the expression of tumor necrosis factor-α (TNF-α) and interleukin-6 (IL-6)." (PMID 35734410, 2022). "This study aimed to explore the value of serum interleukin-1β (IL-1β), interleukin-6 (IL-6), and interleukin-8 (IL-8) combined with carcinoembryonic antigen (CEA) as biomarker panel for the diagnosis and metastasis prediction of lung cancer." (PMID 35928100, 2022). "In lung cancer, CAF‐secreted IL‐6 induces EMT programming and modulate metastasis‐related genes through the JAK2/STAT3 signaling pathway in vitro and in vivo." (PMID 35603909, 2022).
lung carcinoma (continued). "Postoperative IL-6, IL-4, and IFN-γ changes have been suggested as prognostic markers in lung cancer surgery." (PMID 35898583, 2022). "Exosomal miR-21 and miR-29a from lung cancer cells activate mouse TLR7- and human TLR8-mediated NF-κB activation in immune cells and the production of proinflammatory IL-6 and TNF-α to promote lung cancer and metastasis in mice." (PMID 35562884, 2022). "TGF-β and IL-6/JAK2/STAT3 pathway form a positive feedback signal loop, mediating the interaction between MFs and lung cancer cells." (PMID 36591515, 2022). "Reishi increases significantly IFN-γ, IL-2, IL-6, and NK cells (CD56 + cells) levels in lung cancer patients thereby increasing potentially immune therapies." (PMID 35784762, 2022). "Both NFκB-driven and exosomal miR-21a was shown to silence PDCD4, a tumor suppressor and IL-6 inhibitor, promoting the expansion of MDSCs in a IL-6/STAT3 dependant manner in lung cancer." (PMID 35320943, 2022). "TGF-β and IL-6/JAK2/STAT3 signal pathway form a positive feedback signal loop, mediating the interaction between MFs and lung cancer cells." (PMID 36591515, 2022). "The objective of this study was to describe the characteristics of hepcidin, IL-6, and TNF-α levels in anaemia of lung cancer patients with operative tumours." (PMID 36612220, 2022). "To discover small molecules that target IL-6/Laminin α5/FAK signaling in lung cancer, we first performed compound screens in two cell lines (IL-6-GFP PC-9 cells and IL-6-GFP PC-9GR cells) using a small molecule library comprising 510 compounds." (PMID 35197546, 2022). "Six hub genes were screened in relation to lung cancer, including mTOR, NF1, CHD7, ETS1, IL-6, and COL1A1." (PMID 36211008, 2022). "We found that although HIIT did not down-regulate the mRNA level of CD86, it significantly down-regulated the mRNA levels of IL-6, TNF-α, and iNOS in lung cancer tissues, which also functions as an anti-inflammatory role." (PMID 36186906, 2022). "Autophagy induced by TLR4 or TLR3 activation can enhance the production of cytokines such as IL-6, CCL2, MMP2, and CCL20 by promoting TRAF6 ubiquitination, thus facilitating the migration and invasion of lung cancer cells." (PMID 35422093, 2022). "For example, E2F transcription factor 1 (E2F1)-mediated transcriptional upregulation of SNHG3 in lung cancer enhanced the abilities of cell proliferation and migration by activating the TGF-β pathway and interleukin 6 (IL-6) signaling." (PMID 35030969, 2022). "How about the effect of IL-6 antibody combination with CD47 and PD-L1 ICIs in patients with IPF or lung cancer combined with IPF?" (PMID 36544757, 2022). "Clinically, tumors with high stromal Rab37 and IL-6 expression coincide with tumor infiltrating M2-macrophages and PD1+CD8+ T cells that predicts poor prognosis in lung cancer patients." (PMID 34093869, 2021). "Lung cancer cells developed resistance against EGFR tyrosine kinase inhibitors such as gefitinib and erlotinib due to EMT that drives overexpression of IL-6 and IL-8." (PMID 34220337, 2021). "A peak in IL-6 concentrations in patients with stage IIB, IIIA, and IIIB lung cancer, with values of 44.14 pg/mL, 47.36 pg/mL, and 37.00 pg/mL, respectively, was one of the most notable changes in biomarker concentrations in relation to lung cancer stage." (PMID 34439874, 2021). "MPE-Mφ showed relatively higher expression levels of M1 (IL-1β, IL-6, and CXCL10), M2 (CCL18 and IL-10), and pan-macrophage markers (CSF1 and PTPRC) compared to MDMs from lung cancer patients or HCs." (PMID 33175182, 2021). "Elevated levels of IL-6, IL-8, and MCP-1 in lung cancer-derived exosomes significantly enhanced tumor growth." (PMID 34257272, 2021).
lung carcinoma (continued). "IL-6 and BMP control hepcidin secretion in cancer and IL-6 level is elevated in lung cancer patients with poor prognosis." (PMID 34858857, 2021). "LIUS-downregulated innatomic genes were upregulated more than downregulated in proinflammatory cytokine IL-6 KO cells, IL-1β KO, and anti-inflammatory cytokine TGF-β-treated lung carcinoma cells." (PMID 33628851, 2021). "CAFs isolated from human lung cancer tissue secrete IL-6, which stimulates JAK2 and STAT3 signal transduction in human lung cancer cells, thereby increasing metastasis." (PMID 34079469, 2021). "The manifestation of an assemblage of IL-6 and IL-10 or CCR-2, CCL-2 connects to a shoddy projection in patients with lung cancer." (PMID 34336101, 2021). "We observed that Hiltonol+++ (Hiltonol in combination with inhibitors of IL6, JAK2, STAT3) significantly suppressed the viability of lung cancer cells compared to Hiltonol alone." (PMID 33562773, 2021). "First, we treated murine KP lung cancer cells with AZD6244, and observed an increase in TGF-β, IL-6, and IL-23 expression following MEK inhibition." (PMID 33972557, 2021). "LIUS-upregulated IGs were downregulated more than upregulated in proinflammatory cytokine TNF-α KO, IL-6 KO, and anti-inflammatory cytokine TGF-β-treated lung carcinoma cells and ovarian epithelial cells." (PMID 33628851, 2021). "According to in vivo and in vitro lung cancer model studies, TNF-α triggers similar processes as IL-6." (PMID 34336101, 2021). "In summary, the current study demonstrates that Spi-B-positive lung cancer cells play an important role in increasing TAM recruitment by upregulating the expression of various cytokines, such as CSF2, IL6, CCL3, and CCL4." (PMID 34141615, 2021). "TGF-β, IL-6, and TNF-α were increased in the sera and lung lysates of mice with BCG injection and subsequent lung cancer cell injection." (PMID 33567693, 2021). "Accordingly, inhibition of the IL6/STAT3 signaling pathway using an IL6 neutralizing antibody or JAK2/STAT3 inhibitor reverses fibroblast-induced invasion and migration of lung cancer cells." (PMID 34944848, 2021). "CAFs isolated from human lung cancer tissue induce EMT and enhance the metastatic potential of cancer cells by activating the IL-6/STAT3 signaling pathway." (PMID 35087824, 2021). "Both cytokines (IL-6, 10, 17, 27, 35; TNF-α; IFN-γ; TGF-β) and chemokines (CCL-2, 5, 18; CCR-4; CXCR-4; CX3CL-1; CXCL-1, 5, 8, 13) are very commonly targeted for lung cancer treatment, considering their biomarker roles." (PMID 34336101, 2021). "A study showed that Quercetin reduced the production of nickel-induced cytokines, such as IL-1β, IL-6, TNF-α, and IL-10, in lung cancer cell lines." (PMID 33918290, 2021). "Our findings provide a rationale and feasible combined therapeutic approach targeting IL-6 and CTLA-4 in lung cancer patients." (PMID 34093869, 2021). "We found that high hypoxic stress in lung cancer is correlated with inflammatory cytokine secretion and expression in the tumor microenvironment, including IL1A and IL6." (PMID 34362882, 2021). "By treating the lung cancer cells, A549, H460, and H1299, with CoCl2, the mRNA levels of IL1A and IL6 were mildly induced." (PMID 34362882, 2021). "LIUS-upregulated IGs were downregulated more than upregulated in proinflammatory cytokine TNF-α KO cells, IL-6 KO cells, IL-1β KO, and anti-inflammatory cytokine TGF-β-treated lung carcinoma cells." (PMID 33628851, 2021). "Luteolin also inhibits TGF-1-dependent EMT in lung cancer cells by blocking the PI3K/AKT/NF-κB/Snail pathway and also inhibits IL-6-dependent EMT in pancreatic cancer through the prevention of STAT3 signaling." (PMID 34220337, 2021).